CCND1 (cyclin D1)
Diseases named in the same sentence as CCND1 in open-access papers (continued):
Sharing a sentence is not in itself a finding about the gene and the disease.
colon carcinoma (continued). "Despite a well-established role of cyclin-D1 in cell cycle progression, previous data on cyclin-D1 and clinical outcome in colon cancer have been conflicting." (PMID 22050898, 2011). "According to previous studies, increased cyclin-D1 expression occurs in one-third of colonic tumors as an early event during the multistage process of colon carcinogenesis." (PMID 22050898, 2011). "As Cx43 is a downstream target of β-catenin, a key component of Wnt signaling pathway, nuclear accumulation of β-catenin turns on several genes including Cx43, COX-2, cyclin-D1, and PPARδ and contributes to the carcinogenesis of colon cancer." (PMID 21647307, 2011). "IGF-1 treatment elevated pAkt, pGSK3β, and cyclin D1 levels resulting in augmented proliferation of HT-29 colon cancer cells." (PMID 20504360, 2010). "Antisense to cyclin D1 was reported to inhibit the growth and the tumorigenicity of human colon cancer cells and induce apoptosis in human squamous carcinomas." (PMID 18197291, 2008). "It has been suggested that cytoplasmic cyclin D1 is more common in colorectal tumours deficient for β-catenin; however, β–catenin has been shown to regulate cyclin D1 expression in colon cancer cells." (PMID 17375037, 2007). "Treatment of SW480 colon cancer cells with 300 μM resveratrol induced effective clearance of cyclin D1 within 2 h and was inhibited by LLnL." (PMID 17407548, 2007). "In the present study, the expression of cyclin D1 and pRb in 111 cases of resected primary human colon carcinomas was investigated." (PMID 16426443, 2006). "Differences in the pattern of cyclin D1 staining were noted in the colon cancer cases examined in our study." (PMID 16426443, 2006). "The overexpression of the CCND1 gene occurs in more than one-third of all colorectal cancers and adenoma, and expression of an antisense CCND1 cDNA suppresses the growth of colon cancer cells in animal models." (PMID 16495921, 2006). "To confirm this possibility, we performed an immunoprecipitation and immunoblotting (IP-IB) analysis following ectopic expression of Flag-tagged ERK2 with either HA-tagged WT or ΔD cyclin D1 in HCT 116 colon cancer cells." (PMID 17205132, 2006). "Cyclin D1 plays a major role as a potential contributor to the multistep process of oncogenesis; nevertheless its prognostic significance in colon cancer has already been examined in a few studies and needs to be further delineated." (PMID 16426443, 2006). "In colon cancer, ligand activation of PPARγ-mediated differentiation of certain colon cancer cells results in the upregulation of tumour suppressor genes caveolin 1 and 2 and repression of cyclin D1 expression." (PMID 15583697, 2005). "In colon tumours, cyclin D1 was overexpressed in 44%, cyclin D2 was overexpressed in 53% and cyclin D3 was overexpressed in 35% of the cases." (PMID 16012517, 2005). "Cyclin D1 ranks 1009th among significant genes in the colon cancer data set under the t-test but ranks 90th under the PPST test (AB/BA pattern results only)." (PMID 15307894, 2004). "miR‐20b‐5p was shown to function as a tumor suppressor in colon cancer by targeting Cyclin D1." (PMID 40405535, 2025). "A recent study also revealed that decreased expression of Cyclin D1 could inhibit colon cancer cell growth." (PMID 41312374, 2025). "In addition, by IHC, we confirmed that the expression levels of Ki-67 and cyclin D1 (CCND1) were considerably decreased as the drug resistance of colon cancer cells decreased." (PMID 40082673, 2025). "In addition, we found that it downregulates c-myc and cyclin D1, which are normally upregulated in colon cancer to drive tumor proliferation." (PMID 40308769, 2025). "Moreover, microRNA-374a suppresses the progression of colon cancer by directly reducing CCND1 to inactivate the PI3K/AKT pathway." (PMID 38279356, 2024).
colon carcinoma (continued). "Consequently, we observed elevated phosphorylation levels of STAT3 and p65 in LRRK2 G2019S colon tumors, accompanied by upregulation of downstream molecules such as Bcl-xL, cyclin D1 and COX-2." (PMID 38607004, 2024). "Interestingly, MDEs exhibited the opposite effect in colon cancer cells, downregulating β-catenin and cyclin D1 and reducing cell proliferation." (PMID 39769282, 2024). "Importantly, MDEs demonstrated selective activity by downregulating β-catenin and cyclin D1 in colon cancer cells, leading to reduced proliferation." (PMID 39769282, 2024). "Furthermore, using the GEPIA web tool, we found that the mRNA expression of KITENIN positively correlated with that of ß-catenin, c-Myc, cyclin D1, CD44, and HIF-α levels in colon cancer, in which their overexpression is associated with poor survival." (PMID 37553596, 2023). "Expression of ERβ could induce altered cell cycle kinetics by regulating the expression of several components, including cyclin E, cyclin D1 etc., in colon cancer cells." (PMID 36207986, 2023). "To investigate whether β-catenin regulates the expression of cyclin D1 in colon carcinoma cells, we determined its expression after 20d treatment." (PMID 35705657, 2022). "In addition, the expression of cyclin-related proteins (Cyclin C, Cyclin D1, Cyclin E1) in colon cancer cell HT29 in each group was determined by western blot." (PMID 35615948, 2022). "Moreover, esculetin effectively decreased the cell viability and inhibited tumor growth of HCT115, HCT116, and DLD-1 cells, and impaired tumor growth in a colon cancer xenograft mouse model by reducing protein levels of Cyclin D1, c-Myc and Ki-67." (PMID 35053565, 2022). "It was reported that cyclin D1 can be targeted by many miRNAs, such as miR-365 in colon cancer." (PMID 35216636, 2022). "Furthermore, murrayafoline A down-regulates the expression of c-Myc and Cyclin D1 and reduces the viability and proliferation of human colon tumor lines." (PMID 35053565, 2022). "More interestingly, we found that high expression of CCND1 may lead to resistance to multiple anti-colon cancer drugs based on the GSCALite database, which contains 5-fluorouracil, methotrexate, cetuximab and so on." (PMID 34922547, 2021). "Combined with these findings, we speculated that MMP1 might accelerate the cell cycle transition of colon cancer cells by regulating cdc25a/CDK4-cyclin D1 and p21/cdc2-cyclin B1 complexes through alteration in the expression of c-Myc and ETV4." (PMID 34753916, 2021). "Many studies have found that Cyclin D1 is highly expressed in colon cancer and is considered to be an independent factor for poor prognosis, and it could be inhibited by inhibiting NF-κB." (PMID 34531745, 2021). "paracasei reduced the expressions of cyclin D1 and cyclin E1 X12 in HT-29 colon cancer cells." (PMID 34992527, 2021). "Additionally, they indicated that IGF2BP3 repressed the S phase as well as the proliferation of colon cancer by reading m6A modification of CCND1." (PMID 34721530, 2021). "Moreover, nuclear c-Myc and cyclin D1 staining was detected in colon sections from vehicle-treated mice, while colon tumors from SB202190-injected animals showed faint cytoplasmic positivity with a stronger reduction in nuclear areas." (PMID 33767160, 2021). "It was reported that CCNB1 and CCND1 were elevated in colon tumor tissues." (PMID 33996604, 2021). "Consistent with our data, it has been shown that the stimulation of LXR could down-regulate β-catenin targets such as Bmp4, Myc, Cyclin D1, and Mmp7 participating in the survival and proliferation of colon cancer cells." (PMID 33568147, 2021). "Furthermore, mRNA and protein expression of BRD4-dependent genes, including c-Myc, Bcl-2, and cyclin D1, was significantly decreased in A1874-treated colon cancer cells." (PMID 32978368, 2020). "Furthermore, A1874-induced degradation of BRD4 protein and downregulated BRD-dependent genes (c-Myc, Bcl-2, and cyclin D1) in colon cancer cells." (PMID 32978368, 2020).
colon carcinoma (continued). "A recent report suggested that CaSR suppresses the malignant behavior of colonic cancer cells by regulating the Wnt signaling pathway including GSK3β and Cyclin D1, which was proved to be vitally important in the development and the growth of LUAD in previous studies, including ours." (PMID 32671062, 2020). "PPI and pH8 treatment (alkalization) of CMT93 mouse colon cancer cells inhibited cell growth and invasion, increased oxidative stress and apoptosis, and decreased mitochondrial volume and protein levels of cyclin D1 and phosphorylated extracellular signal-regulated kinase (pERK) 1/2." (PMID 32485921, 2020). "Inhibition of SUMO1P3 repressed proliferation, migration, invasion and pro-angiogenesis of colon cancer cells in vitro, and reduced growth, liver metastasis and vascularization of colon cancer in vivo by decreasing cyclin D1, vimentin and VEGFA but increasing E-cadherin expression." (PMID 32185172, 2020). "Similar findings have been shown in cervical carcinoma (HeLa), where IMP significantly inhibited the tumor necrosis factor (TNF)-α-induced expression of cyclin D1 and in HT-29 colon cancer cells affected by IMP treatment, resulting in cell cycle arrest in the G1 phase and apoptosis induction." (PMID 32353989, 2020). "For example, CCND1 promotes the colon cancer development via PI3K/Akt pathway." (PMID 31340767, 2019). "CCND1 was upregulated in carcinoma tissue and was associated with 11 miRNAs, nine of which had seed matches, including hsa-miR-106b-5p, hsa-miR-17-5p, hsa-miR-20a-5p, hsa-miR-20b-5p, and hsa-miR-93-5p; these miRNAs have been reported to target CCND1 and be over expressed in colon cancer." (PMID 29725503, 2018). "In addition, the upregulated expression of cyclin D1 promotes the proliferation of HT29 human colon cancer cells." (PMID 30279365, 2018). "Furthermore, we found that the expression level of the KLF6-SV1 was not correlated with cyclin D1 (p = 0.816), which supports that wtKLF6 negatively regulates cyclin D1 in NPC as previously reported in colon cancer cells." (PMID 29854578, 2018). "Butyrate has been shown to downregulate Wnt activity in CC531 rat colon carcinoma cells by reducing the expression of 4 Wnt target genes that are upregulated in CRC [CCND1, c-MYC, FOSL1, and follistatin (FST)], but it has also been shown to induce Wnt signaling leading to stimulated apoptosis." (PMID 28077379, 2017). "DNA replication and cellular proliferation (annotated by Mod102) related protein Ki-67 and cyclin D1 could predict benefit from adjuvant chemotherapy in colon cancer." (PMID 29237416, 2017). "Moreover, it has been reported that a curcumin analogue ((1E, 6E)-1, 7-di (1H-indol-3-yl) hepta-1, 6-diene-3, 5-dione) down-regulated cyclin D1 and activated Caspase 3, 8 and 9 in lung adenocarcinoma (A549), leukemia (K562) and colon cancer (SW480) cells." (PMID 28566729, 2017). "γ-Tocotrienol and δ-tocotrienol, both of which are vitamin E derivatives, were found to reduce the level of expression and nuclear localisation of β-catenin in colon cancer cell lines, leading to reduced expression of cyclin D1, c-myc and survivin in these cells." (PMID 28672811, 2017). "In colon cancer, overexpression of cyclin D1 is observed in 55% of patients." (PMID 28414818, 2017). "Moreover, genetic alteration in claudin-2 expression was sufficient to modulate cyclin-D1 and P-21 expressions in colon cancer cells and modulate growth properties." (PMID 29152115, 2017). "The number of cells displaying membranous or cytoplasmic Ccnd1 was significantly higher in peripheral cells than in inner cells in both collective and pushing invasion patterns of endometrial carcinoma, and in collective invasion pattern of colon carcinoma." (PMID 27105504, 2016). "Furthermore, overexpression of β-catenin enhances the expression of cyclin D1, a critical factor for G1/S transition during cell cycle progression in colon carcinoma cells." (PMID 27733866, 2016).
colon carcinoma (continued). "We previously reported CCND1 was suppressed by miR-374a in colon cancer." (PMID 27191497, 2016). "Also, a significant decrease in cyclin d1 mRNA was observed in colon tumors of combination-dose treatment." (PMID 27841323, 2016). "Aberrant activation of PI3K/Akt/mTOR and MAPK/ERK pathways may induce colon tumor growth and progression by increasing β-catenin and cyclin-D1 expression." (PMID 27895803, 2016). "Human SW-480 colon tumor cells were used to determine the translocation of β-catenin into the nucleus where it binds to the Tcf/Lef transcription factor and induces the transcription of survival proteins such as survivin and cyclin D1." (PMID 26713600, 2016). "Furthermore, dose-dependent inhibition of COX-2 using NS398 inhibited the expression of Bcl-3 and cyclin D1 in a human colon cancer cell line." (PMID 25929479, 2015). "These inhibitory effects were accompanied by mechanistic down-regulation of the protein levels of cyclooxygenase-2 (COX-2), matrix metallopeptidase-9 (MMP-9), vascular endothelial growth factor (VEGF), and cyclin D1, as well as by the induction of apoptosis in colon tumors." (PMID 25389774, 2014). "In the present study, our data show that miR-145 downregulates c-Myc and its target gene cyclin D1, as supported by the findings in other cancers that miR-145 represses the expression of c-Myc and its downstream targets in colon cancer and non-small cell lung cancer (NSCLC)." (PMID 23710609, 2013). "Moreover combined knockdown of Sp1, Sp3 and Sp4 using an oligonucleotide cocktail (iSp) also decreased expression of p65, PTTG-1, EGFR and cyclin D1 in RKO cells confirming their regulation by Sp transcription factors in colon cancer cells." (PMID 21864401, 2011). "There were highly significant differences between the rectal and the colon cancers in the protein expression of cyclin D1, cyclin D3, cyclin E, nuclear β-catenin, and c-Myc, even when adjusted for Dukes' stage, differentiation grade, gender, and age of patient at the time of surgery." (PMID 20029639, 2009). "Similarly, culture of HCT116 colon cancer cells with the MEK inhibitor U0126 extended the half life of cyclin D1 and abolished T286 phosphorylation." (PMID 17407548, 2007). "In our study, the proliferate activity (Ki-67 protein expression) in colon cancer cases was correlated with cyclin D1 levels (P = 0.045) suggesting that cyclin D1 contributes to an increased proliferate potential that might be adequate in colon cancer cases." (PMID 16426443, 2006). "The presence of cytoplasmic pattern could suggest that not only elevated cyclin D1 levels occurring in colon cancer tumoral cells but alterations in the transport of the protein in the nucleus also exist." (PMID 16426443, 2006). "Although overexpression and rearrangement of cyclin D1 gene are associated with tumour progression and/or poor prognosis in various tumour types, in colon cancer the link to prognosis is not clear." (PMID 16012517, 2005). "Overexpression of cyclin D1 in colon cancer is well established." (PMID 16012517, 2005). "Cyclin D1 overexpression has been reported to occur in 40–70% of colon tumours." (PMID 16012517, 2005). "Furthermore, the overabundance of ZKSCAN3 correlates with elevated levels of several factors that contribute to colon cancer progression, including integrin, cyclin D1 (CCND1), epidermal growth factor receptor (EGFR), and vascular endothelial growth factor (VEGF)." (PMID 39519085, 2024). "We noted a slight inhibition of cyclin D1 expression in 20d-treated cells compared with the DMSO-treated cells after 72 h of treatment, which might be associated with its induction of growth arrest in colon cancer cells." (PMID 35705657, 2022). "In addition, CCND1 could interact with other factors to act as a proliferation promoter of colon cancer." (PMID 36612120, 2022).
colon carcinoma (continued). "To examine whether elevated CREPT level correlates to the expression of STAT3-downstream genes, we analysed the messenger RNA (mRNA) levels of several key genes including c-MYC, CCND1 and Bcl-XL in breast and colon cancers from The Cancer Genome Atlas RNA-sequencing database." (PMID 33531691, 2021). "Since cyclin D1 acts as a transcriptional regulator of cell proliferation and migration, and Atox1 is known to induce cyclin D1 transcription, we hypothesized that Atox1 could positively regulate colon cancer metastasis by influencing cyclin D1 expression." (PMID 31961892, 2020). "Therefore, we conclude that Tet and the CCND1/CDK4 compound could form hydrogen bonds and a stable compound structure, which can inhibit colon cancer cells proliferation by regulating CCND1/CDK4 compound and its downstream proteins phosphorylated Rb (p-Rb)." (PMID 31040202, 2019). "However, it has been shown that the Mastermind-like 1 co-activator of Notch pathway can bind to the promoters of Cyclin D1 and Myc in colon cancer cell lines and these molecules are activated directly by Notch1 in other types of cancer and possibly by Cyclin D1 in CRC." (PMID 28086833, 2017). "Thus, the importance of cyclin D1 expression seems to be complex and different between tumors, and therefore, our study encourage further and larger studies for cyclin D1 expression in colon cancer, in order to verify if the expression of this molecule indicates poor prognosis." (PMID 16426443, 2006). "Even though cyclin D1 and pRb have not disclosed any clear association with shorter survival, cyclin D1 positivity may be a useful predictor of subgroup patients with colon cancer being in advanced stage and early age." (PMID 16426443, 2006). "Proteomics screens in HCT116 colon carcinoma and KELLY neuroblastoma cells, found that niclosamide induces rapid cyclin D1 degradation through a mechanism involving the ubiquitin-proteasome pathway." (PMID 40337304, 2025). "Butyrate also inhibits STAT3 signaling, thus suppressing the expression of bcl-2, bcl-XL, c-myc, cyclin D1, and HIF-1, resulting in decreased cell proliferation and increased apoptosis in both hypoxia and in colon cancer." (PMID 40699627, 2025). "Our results indicated IRSp53 upregulation in patients suffering colon cancer and reduction of EGFR/c-Src/IRSp53/p-AKT/p-Stat3/cyclin D1 signaling pathway, which led to suppression of cell proliferation in the hAMSCs-treated HT-29 colon cancerous cells." (PMID 41200137, 2025). "In colon cancer cells, miR-93 downregulated the Wnt/β-catenin pathway, which was confirmed by measuring the expression of β-catenin, AXIN, c-Myc, and cyclin D1 in this pathway." (PMID 40693022, 2025). "In conclusion, AFC inhibits colon cancer growth by downregulating PKM2 to inhibit aerobic glycolysis and reduce the tumor-specific high expression of c-myc and cyclin D1." (PMID 40308769, 2025). "Akt is a key player in the growth of colon tumors; it stops GSK3β/APC/axin from breaking down β-catenin and increases the expression of oncogenes like c-Myc and cyclin D1 that target β-catenin." (PMID 39811247, 2025). "It is IGF2BP3 that targets cyclin D1 and VEGF to regulate the cell cycle and angiogenesis of colon cancer." (PMID 38355626, 2024). "This interaction stimulates SMAD3 phosphorylation and activates the SMAD2-3-4 signaling pathway, resulting in the inhibition of cyclin D1/CDK4 expression and leading to G1 cell cycle arrest in colon cancer cells." (PMID 38338430, 2024). "This study revealed that remimazolam promoted the cell-cycle progression and proliferation of HCT8 colon cancer cells by upregulating CDK1, PTTG1, CDC25C, CDK4, PLK1, PCNA, Ki67, RNASEH2B, FEN1, Cyclin D1,CD44 CDK2, CDKN3, CDC45, IQGAP3, and CDK6." (PMID 38725628, 2024).